KCNA4 (potassium voltage-gated channel subfamily A member 4)
Description:
Voltage-gated potassium channel that mediates transmembrane potassium transport in excitable membranes. Forms tetrameric potassium-selective channels through which potassium ions pass in accordance with their electrochemical gradient. The channel alternates between opened and closed conformations in response to the voltage difference across the membrane. Can form functional homotetrameric channels and heterotetrameric channels that contain variable proportions of KCNA1, KCNA2, KCNA4, KCNA5, and possibly other family members as well; channel properties depend on the type of alpha subunits that are part of the channel. Channel properties are modulated by cytoplasmic beta subunits that regulate the subcellular location of the alpha subunits and promote rapid inactivation. In vivo, membranes probably contain a mixture of heteromeric potassium channel complexes, making it difficult to assign currents observed in intact tissues to any particular potassium channel family member. Homotetrameric KCNA4 forms a potassium channel that opens in response to membrane depolarization, followed by rapid spontaneous channel closure. Likewise, a heterotetrameric channel formed by KCNA1 and KCNA4 shows rapid inactivation.
Synonyms: KCNA4L; Kv1.4; HK1; HPCN2; PCN2; HBK4; HUKII; KCNA8; MCIDDS
Tractability: Small molecule: an approved drug acts on it; a high-quality ligand is known; it belongs to a druggable protein family. Antibody: UniProt places it where antibodies can reach, with high confidence; its Gene Ontology location is reachable by antibodies, with high confidence; UniProt predicts a signal peptide or a membrane-spanning region. PROTAC: its protein half-life has been measured; a small molecule that binds it is known.
Target class: Potassium channels; Ion channel; Voltage-gated ion channel; Voltage-gated potassium channel
Gene: Protein-coding gene on chromosome 11 (30,009,552 to 30,017,030, reverse strand). Ensembl gene ENSG00000182255.
Subcellular location: Cell membrane; Cell projection, axon
Pathways (Reactome):
Neuronal System: Voltage gated Potassium channels
Gene Ontology:
Molecular function: protein binding; voltage-gated potassium channel activity; delayed rectifier potassium channel activity; monoatomic ion channel activity; potassium ion binding; voltage-gated monoatomic ion channel activity involved in regulation of presynaptic membrane potential
Biological process: potassium ion transmembrane transport; action potential; potassium ion transport; monoatomic ion transport; protein homooligomerization; regulation of presynaptic membrane potential; transmembrane transport
Cellular component: plasma membrane; voltage-gated potassium channel complex; axon; dendritic spine; membrane; axon initial segment
Genetic constraint (gnomAD): Loss-of-function variants: 5 observed, 38.49 expected, observed/expected ratio (o/e) 0.13, 90% interval 0.067 to 0.27. The upper end of that interval is the gene's LOEUF score, 0.27, which puts it in group 1 of 6, group 1 being the genes least tolerant of losing a copy. Missense variants: 634 observed, 851.67 expected, observed/expected ratio (o/e) 0.74, 90% interval 0.7 to 0.8. Synonymous variants: 350 observed, 328.53 expected, observed/expected ratio (o/e) 1.07, 90% interval 0.98 to 1.16.
Homologues: Orthologues: macaque KCNA4 (99% identical), rabbit KCNA4 (98% identical), rat Kcna4 (98% identical), mouse Kcna4 (97% identical), guinea pig KCNA4 (91% identical), dog KCNA4 (89% identical), pig KCNA4 (88% identical), tropical clawed frog kcna4 (74% identical), zebrafish kcna4 (69% identical). Paralogues in human: KCNA3 (54% identical), KCNA2 (53% identical), KCNA1 (52% identical), KCNA5 (50% identical), KCNA6 (50% identical), KCNA10 (47% identical), KCNA7 (45% identical), KCNC4 (29% identical), KCNC3 (28% identical), KCNC2 (28% identical), KCNC1 (28% identical), KCNB2 (27% identical), and 19 more.
Diseases named in the same sentence as KCNA4 in open-access papers:
KCNA4 is named in the same sentence as 53 diseases in open-access papers, as found by Europe PMC text mining. Sharing a sentence is not in itself a finding about the gene and the disease. The quoted sentences say what the papers report.
Arrhythmia (4 papers, 2015 to 2023). Any cardiac rhythm other than the normal sinus rhythm. "miR-155 might directly influence arrhythmia outcomes by targeting critical ion channel gene expression, including CACNA1C and KCNA4, which encode the cardiac L-type Ca2+ channel (ICaL) α1c and the initial component of the transient outward potassium current (Ito1), respectively." (PMID 26319023, 2015).
glioma (3 papers, 2021 to 2025). A benign or malignant brain and spinal cord tumor that arises from glial cells (astrocytes, oligodendrocytes, ependymal cells). "Although there is limited information around how KCNA4 is associated with tumors, other members from the potassium voltage-gated channel family such as Kv1.3 and Kv1.5 are well-studied and have shown correlations with several human cancers including gliomas." (PMID 33498463, 2021). "Research has also noted a relationship between methylation patterns at CpG sites targeting SMOC1, KCNA4, SLC25A21, and UPP1, and the molecular characteristics of glioma, such as IDH mutations and 1p/19q co‐deletions, which aligns with our findings." (PMID 40781854, 2025). "Regarding Kv1.4, the KCNA4 methylation pattern increased along with tumor grade progression and the predicted poor survival of glioma patients." (PMID 36978819, 2023). "The KCNA4 CpG sites we identified indicate worse patient survival in the hypermethylated group correlating with decreased gene expression as glioma grade progresses." (PMID 33498463, 2021). "Further investigation on how KCNA4 expression and methylation impact glioma is needed." (PMID 33498463, 2021). "Gene expression of SMOC1, KCNA4, and SLC2521 declined as patient glioma grade increased while UPP1 gene expression showed a positive relationship with tumor grade." (PMID 33498463, 2021). "CpG site of UPP1 demethylate as glioma grade increases while the remaining genes, SMOC1, KCNA4, and SLC25A21, methylate along with higher tumor grade." (PMID 33498463, 2021). "Our study highlights genes (KCNA4 and SLC25A21) that were not previously associated with gliomas to have contributed to the poorer patient outcome." (PMID 33498463, 2021).
diabetic neuropathy (2 papers, 2020 to 2022). A chronic, pathological complication associated with diabetes mellitus, where nerve damages are incurred due to diabetic microvascular injury involving small blood vessels that supply these nerves, resulting in peripheral and/or autonomic nerve dysfunction. "Five of them, KCNA2, KCNA4, KCNQ5, KCNN1 and KCNS1, were also negative for screening in a diabetic neuropathy population." (PMID 36430572, 2022).
behavioral disorders (1 paper, 2018). "Some candidates have been linked to intellectual disability (ID), such as CRBN, GPKOW, HERC1 and KCNA4, or to other behavioral disorders, such as CDC42EP4 and SLITRK5." (PMID 30102725, 2018).
cataract (1 paper, 2020). Partial or complete opacity of the crystalline lens of one or both eyes that decreases visual acuity and eventually results in blindness. "The phenotypes for KCNA4 deficiency include microcephaly, cataracts, impaired intellectual development, and dystonia with abnormal striatum (OMIM: 618214)." (PMID 32446308, 2020).
Cognitive impairment (1 paper, 2018). Abnormal cognition is characterized by deficits in thinking, reasoning, or remembering. "KCNA4 encodes a voltage-gated potassium channel, and mutations in KCNA4 have been identified in patients exhibiting linguistic disabilities, attention deficit hyperactivity disroder (ADHD), and cognitive impairments." (PMID 29345619, 2018).
dilated cardiomyopathy (1 paper, 2025). Cardiomyopathy which is characterized by dilation and contractile dysfunction of the left and right ventricles. "In addition, upregulation of Kcna4 and downregulation of Ckmt2, genes linked to dilated cardiomyopathy and arrhythmia, have been observed in cardiac-specific MBNL1 and MBNL2 double-knockout mice and were also misregulated in CUG960 +dox mice." (PMID 39932794, 2025).
oral cancer (1 paper, 2024). "Moreover, SCC15-specific upregulation was observed with KCNA4 and SRGAP2 and downregulation among SCC15 cells of FAM135A, which was observed among all other oral cancer cell lines." (PMID 38396844, 2024). "However, three miR-145 downstream targets were identified in the least chemotherapy-resistant cells, exhibiting the differential upregulation of KCNA4 and SRGAP2, as well as the downregulation of FAM135A, with this expression pattern not detected in any of the other oral cancer cell lines." (PMID 38396844, 2024).
pituitary adenomas (1 paper, 2020). "Druggable genes shared by all types of pituitary adenomas included NRG1, KCNA4, NCAM1, GRIA2 and GRM8." (PMID 33168897, 2020).
renal cell carcinoma (1 paper, 2024). "Moreover, this study also demonstrated the association between miR-145 upregulation and positive expression of the potassium voltage-gated channel protein KCNA4, which was also recently identified in a genome-wide differential expression study of renal cell carcinomas." (PMID 38396844, 2024).
cancer (3 papers, 2020 to 2023). A tumor composed of atypical neoplastic, often pleomorphic cells that invade other tissues. "Whether KCNA4 hypermethylation correlates with high expression of the channel and the effects of altered expression/functions in cancer cells still await clarification." (PMID 36978819, 2023). "We evaluated the overall genetic alterations in all KCNA genes (KCNA1, KCNA2, KCNA3, KCNA4, KCNA5, KCNA6, KCNA7, KCNA10) using the TCGA Pan-Cancer Atlas dataset, collecting data from 32 human cancers (10,953 patients in total)." (PMID 36978819, 2023).
KCNA4 also shares sentences with these, for which no sentence is quoted: thymoma (5 papers); heart failure (4); myocarditis (4); tumor (3); epilepsy (2); Epileptic encephalopathy (2); injury (2); Myasthenia (2); myasthenia gravis (2); myopathies (2); myositis (2); amyotrophic lateral sclerosis (1); Ataxia (1); AV block (1); breast carcinoma (1); cardiac arrhythmias (1); cardiac hypertrophy (1); channelopathies (1); cystitis (1); Dystonia (1); epileptic seizures (1); episodic ataxia (1); episodic ataxia type 1 (1); gastric cancer (1); gynecological cancers (1); headache disorder (1); Intellectual disability (1); ischemia (1); Lambert-Eaton myasthenic syndrome (1); memory (1).
A further 12 diseases each share a sentence with KCNA4 in 1 paper.